CD36 (CD36 molecule (CD36 blood group))
Diseases named in the same sentence as CD36 in open-access papers (continued):
Sharing a sentence is not in itself a finding about the gene and the disease.
Insulin resistance (continued). "Thus, CD36 plays an essential role in the early stage development of insulin resistance due to lipid overload." (PMID 31938068, 2020). "Previous evidence demonstrated that regulating CD36 expression in the liver could be related to insulin resistance and also prevented lipid accumulation of rats fed a high-fat diet." (PMID 32410994, 2020). "Disruption of hepatic CD36 has been shown to reduce both lipid content and free fatty acid uptake in the liver of HFD-fed mice, and also to protect against associated systemic inflammation and insulin resistance." (PMID 32825073, 2020). "CD36 plays a key role in this process leading to pathological accumulation of lipids (TAGs, DAGs and CERs) in non-adipose organs, such as liver, heart and muscle (ectopic lipid accumulation), and initiating lipotoxicity and insulin resistance." (PMID 32796572, 2020). "Moreover, CD36 mediates a proinflammatory signaling loop between adipocytes and macrophages, which promotes insulin resistance in response to hyperlipidaemia." (PMID 32796572, 2020). "Though the detail mechanism between insulin resistance and CD36 expression is still unknown, the down-regulation of CD36 might be relate to the improvement of insulin resistance." (PMID 29593573, 2018). "Our results suggested that STAMP2 gene overexpression may improve insulin resistance via attenuating angiogenesis in epididymal and brown adipose tissues through the PPARγ/CD36 signalling pathway." (PMID 28631352, 2017). "In addition, a wide variety of studies have investigated the important roles CD36 plays in many disorders, such as coronary heart disease, hypertension, Alzheimer's Disease, insulin resistance, and metabolic syndrome." (PMID 28804718, 2017). "CD36 has the ability to facilitate the uptake of long-chain fatty acids in muscle and adipose tissues, which contributes to the regulation of lipid metabolism and insulin resistance." (PMID 28804718, 2017). "Published data are contradictory on the effect of CD36 on the development of insulin resistance." (PMID 28729885, 2017). "Furthermore, RCR restored fructose-induced sarcolemmal overexpression and intracellular less distribution of fatty acid translocase/CD36 that contributes to etiology of insulin resistance by facilitating fatty acid uptake." (PMID 27405506, 2016). "However, this study still cannot exclude the role of adipose CD36 in RCR extract treatment-elicited amelioration of insulin resistance." (PMID 27405506, 2016). "While CD36 soluble receptor levels are considered an early marker of insulin resistance, it could also be considered that modulation of scavenger receptor could represent a precompensation mechanism in individuals with an altered metabolism." (PMID 27525284, 2016). "It would be interesting to further investigate whether RCR extract, salidroside, mangiferin and other herb-derived insulin sensitizers share the similar mechanisms to modulate CD36 in ameliorating insulin resistance." (PMID 27405506, 2016). "Thus, our data provide evidence for a direct role for hyperinsulinemia in stimulating hepatic Cd36 expression and thus the development of hepatosteatosis, hepatic insulin resistance, and dysglycemia." (PMID 26085100, 2015). "Moreover, CD36 expression is increased and positively correlates with plasma insulin levels, insulin resistance, and the degree of steatosis in NAFLD patients." (PMID 26085100, 2015). "Hepatic expression of Cd36, a fatty acid transporter, is enhanced in obese and diabetic murine models and human nonalcoholic fatty liver disease, and thus it correlates with hyperinsulinemia, steatosis, and insulin resistance." (PMID 26085100, 2015). "Besides its implicated role as a prototype inflammatory receptor in acute cerebral ischemia, CD36 in the plasma was identified as a novel marker of insulin resistance." (PMID 24886035, 2014).
Insulin resistance (continued). "In contrast, one study has suggested that CD36 deficiency, characterized by the absence of CD36 expression in peripheral platelets alone or both platelets and monocytes, is associated with insulin resistance in patients with coronary heart diseases." (PMID 24016701, 2013). "Therefore, opinions concerning a direct or indirect role of CD36 in insulin resistance and the development of type II diabetes are diverging." (PMID 22662181, 2012). "CD36 could then function as a molecular bridge between the development of dyslipidaemia and insulin resistance." (PMID 22662181, 2012). "Defect function or expression of CD36 can result in dyslipidemia or insulin resistance." (PMID 17640331, 2007). "The finding that G allele carriers have a lower weight and better GIR than non-carriers could suggest that CD36 deficiency protects against weight gain and muscle insulin resistance but this needs further testing in larger cohorts." (PMID 39503770, 2025). "Interestingly, it was shown that long-chain FAs (C16:0 and C18:0) in vitro or in vivo induce a loss of endosomal acidification by v-ATPase inhibition and consequently the translocation of CD36 to the cell surface, which in the long term leads to insulin resistance." (PMID 40643519, 2025). "Some studies have shown that upregulation of CD36 is associated with insulin resistance, suggesting that CD36 may be a negative mediator of insulin sensitivity." (PMID 36979708, 2023). "It is hypothesized that, in contrast to the absence of PA loading, loss of CD36 protects against insulin resistance in the presence of PA overload due to a reduction in lipid accumulation." (PMID 36979708, 2023). "For example, CD36 deletion in endothelial cells could increase plasma free fatty acids (FFA) and postprandial TG levels and its deletion in lymphatic endothelial cells caused visceral obesity and insulin resistance." (PMID 35721211, 2022). "Moreover, CD36-associated JNK activation correlated with the impaired tyrosine phosphorylation of IRS-1, and IRS-2 blocks interaction with phosphoinositide 3-kinase (PI3K), thereby inducing insulin resistance." (PMID 34360006, 2021). "CD36 inhibition may prevent visceral obesity and improve insulin resistance." (PMID 32796572, 2020). "Last but not least, association was then demonstrated between human CD36 and insulin resistance." (PMID 32741357, 2020). "Although CD36 is also particularly abundant in adipose tissue, it is still unclear whether CD36 function in adipocytes influences ectopic fat distribution and the pathogenesis of insulin resistance in muscle and liver." (PMID 27405506, 2016). "Given the critical role of insulin resistance in these patients it was informative in that molecules immediately down stream of the insulin receptor appeared to be down regulated, such as IRS1, CD36 and JAK1/2 (a tyrosine kinase associated with cytokine and metabolic signalling)." (PMID 18997871, 2008). "Although the current studies suggest that CD36 contributes to the development of T2DM on two levels, insulin resistance and pancreatic β-cell dysfunction and damage, the role of CD36 in the pathogenesis of DM is unclear." (PMID 40565598, 2025). "Nicotinamide mononucleotide prevented CD36-mediated lipid accumulation and CD36-TLR4 interaction, thereby reducing inflammation, fibrosis, cardiac dysfunction, and whole-body insulin resistance." (PMID 39290498, 2024). "Insulin resistance stimulates AMPK (an energy-sensing enzyme in low energy), increases FFAs intake in the heart via CD36." (PMID 39396974, 2024). "It ameliorates insulin resistance, oxidative stress, and inflammation in T2DM mice in skeletal muscle and also inhibits CD36 expression in adipocytes." (PMID 39125700, 2024). "Among these pathways, PPARGC1A, CD36, IRS2, PCK2, and IGF1 were enriched in the AMPK signaling pathway, and PCK2 was additionally enriched in the adipocytokine signaling pathway and insulin resistance." (PMID 37958518, 2023).
Insulin resistance (continued). "Using HFD-induced NAFLD mice model, we conducted knock-down or OE of DKK1 specifically in the liver and found that DKK1 was a key player of steatosis and insulin resistance, and DKK1-driven steatosis is CD36-dependent through ERK-PPARγ signaling." (PMID 36410795, 2023). "Studies found that the elevation of CD36 protein increases cellular FFA uptake and correlates with insulin resistance in diabetes, demonstrating the potential role of CD36 in affecting glucose and lipid metabolism in T2DM." (PMID 36185686, 2022). "Even current finding has shown the pivotal role of another angiogenic regulator, angiopoietin 2 (ANGPT2), in modulating FAT/CD36 and FATP3 expression through integrin α5β1 signaling and key to insulin resistance." (PMID 34529222, 2022). "It should be noted that BCL6 upregulation in hepatocytes was sufficient in inhibiting CD36 gene expression and lipid accumulation in the liver, resulting in an overall improvement in HFD mice insulin resistance." (PMID 35436984, 2022). "Thereafter, recruitment of CD36 and glucose transporter GLUT4 to the sarcolemma become impaired (insulin resistance)." (PMID 35125400, 2022). "During insulin resistance and NAFLD, there is an increase in peripheral lipolysis with an intrahepatic influx of FFA, internalized by a system involving CD36, overexpressed in insulin resistance states." (PMID 34065331, 2021). "In particular, genes whose transcription supresses insulin resistance and T2DM, such as CD36, adiponectin, adipsin, and leptin, are downregulated by Thrap3 binding to pPPARγ." (PMID 34339734, 2021). "The dysregulation of the CD36-dependent pathways of FA and glucose metabolism in skeletal muscles, occurring in chronic excess of FA and DM, may reduce their ability to modulate FA, and glucose utilization depends on energy needs, which will result in lipid accumulation and insulin resistance." (PMID 32796572, 2020). "Suppression of CEACAM1, GLUT2, and PON1, and elevation of CD36, PCK1, and G6PK were also found to be characteristic in hyperglycemic HepG2 cells compared with normoglycemic cells, suggesting insulin resistance and NAFLD." (PMID 31805072, 2019). "Therefore, we could not elucidate the relationship between CD36 deficiency and insulin resistance in patients with CLD-C." (PMID 24016701, 2013). "Serum analysis further revealed that hepatic Cd36 knockout significantly reduced circulating levels of TG, TC, NEFA, and LDL while increasing HDL in HD mice, indicating amelioration of DRF-induced dyslipidemia and insulin resistance." (PMID 40562101, 2025). "Since insulin resistance is associated with hyperinsulinemia, it is also consistent with our observation of no plasma insulin induction by HFD in the Apoe/Cd36 double-null mice." (PMID 39156133, 2024). "Hence, upon full development of insulin resistance in cardiac cells, the subcellular distribution of GLUT4 becomes juxtaposed to that of CD36, with GLUT4 being inside and CD36 outside." (PMID 35888703, 2022). "In addition, one strain of spontaneously hypertensive rats lacks CD36 and shows metabolic phenotypes of insulin resistance and high free fatty acid (FFA) levels, which are ameliorated by the transgenic overexpression of CD36." (PMID 33995128, 2021). "In spite of this, mice lacking CD36 are protected from insulin resistance, even under a high-fat diet." (PMID 33854480, 2021). "The mechanism underlying the positive association between the sCD36 and T2DM is not clearly defined, but current reports implicate that CD36 contributes to the development of T2DM on two levels: insulin resistance and pancreatic β-cell dysfunction and damage." (PMID 32796572, 2020). "The contribution of CD36 to the modulation of mitochondrial function in insulin resistance is not clear." (PMID 32796572, 2020). "Although we did not observe a concomitant reduction in PPAR and CD36 in adipose tissue, we did observe reduction of the insulin resistance markers RBP4 and resistin in this organ." (PMID 29691457, 2018).
Insulin resistance (continued). "Studies have reported strong evidence that suggests YKL-40, α-HB, soluble CD36, leptin, resistin, IL-18, RBP4, and chemerin could be new biomarkers for the pathogenesis of insulin resistance and endothelial dysfunction in T2DM patients." (PMID 24282409, 2013). "Given the many functions of CD36 including long chain fatty acid transport (LCFA), changes in CD36 expression and protein may lead to several disturbances including insulin resistance and dyslipidemia." (PMID 24188362, 2013). "In addition, reversal of insulin resistance in ob/ob mice with rosiglitazone, a peroxisome proliferator-activated receptor (PPAR) γ agonist, leads to decreased CD36 expression on PerMΦs." (PMID 17551591, 2007). "CD36 gene knock out, however, did not induce insulin resistance in mice." (PMID 22662181, 2012). "The gene expression of PPARγ and its target genes CD36, LDL in whitefat tissue, and PPARα and its target gene ACO in liver were also elevated in CE-treatedDIO mice indicating that CE may act as a dual activator of PPARγ and PPARαresulting in improved insulin resistance and lowered serum lipids." (PMID 19096709, 2008). "Salvionolic acid B (SAB) decreases vWAT and improves insulin resistance in WT obese mice, but not in CD36-depleted mice, suggesting that SAB can specifically inhibit CD36." (PMID 39125923, 2024). "As the patients in each age subgroup were matched in terms of sex distribution, body mass index, insulin resistance score (HOMA) and histological grade of steatosis (in the case of the NAS group), these parameters do not explain the differences seen in CD36 expression in our human study." (PMID 24751397, 2014). "Similarly, C3H mice, which lack Pparγ expression in the liver, did not enhance hepatic Cd36, Fabp4, and Mogat1 expression on the SRD diet or in response to liver insulin perfusions, and furthermore, they did not develop hepatosteatosis and hepatic insulin resistance in response to the SRD." (PMID 26085100, 2015).
breast carcinoma (161 papers, 2015 to 2026). "Clinical data suggest that increased CD36 expression after anti-HER2 therapy is associated with poor prognosis in breast cancer patients." (PMID 40256431, 2025). "The activated HER2/PI3K/AKT/mTOR signaling pathway positively correlated with SCD-1 and CD36 expression in PTEN-loss breast cancer cells." (PMID 39920872, 2025). "Exogenous fatty acid intake can cause overexpression of CD36 in malignancies, including breast carcinoma, stomach carcinoma, and ovarian carcinoma." (PMID 40956032, 2025). "For example, high mammographic density (MD) is a significant risk factor associated with an increased incidence of breast cancer, and high MD (but cancer-free) tissue shows reduced levels of CD36." (PMID 38276607, 2024). "Particularly, CD36-mediated metabolic reprogramming in breast cancer, has been linked to resistance to HER2-targeted therapies." (PMID 37700339, 2023). "Fatty acid receptor CD36 is associated with the prognosis and metastasis of Luminal A breast cancer." (PMID 37179822, 2023). "In particular, CD36-mediated metabolic adaptations have been implicated in lipid-dependent breast cancer aggressive phenotypes, including metastasis, resistance to HER2-targeted therapy and modulation of the tumor microenvironment by T-cell dysfunction." (PMID 37377750, 2023). "When CD36 is deficient, Luminal A breast cancer metastasis is inhibited, and the survival rate is high, suggesting that it is relevant to prognosis." (PMID 37179822, 2023). "Recent studies have implicated CD36 in promoting the resistance of breast cancer towards tamoxifen, a widely used selective ER modulator for treating ER+ breast cancer." (PMID 35448537, 2022). "The Cd36 down-regulation was also observed in primary tumor epithelium, and its possible association with breast cancer metastases was reported." (PMID 35388653, 2022). "For instance, the metastatic dissemination of breast cancer is correlated with the secretion of breast-associated adipocytes via induced CD36 expression." (PMID 36428985, 2022). "CD36 expression correlates with poor disease-free survival in patients with squamous cell lung carcinoma and bladder and breast cancers, possibly because the predisposition to accumulate and metabolise lipids initiates metastasis." (PMID 34983949, 2022). "The secretion of breast-associated adipocytes induced CD36 expression, thereby enhancing the ability of breast cancer cells to uptake fatty acid and their invasiveness in vitro." (PMID 35071325, 2021). "Gain- and loss-of-function studies, with stable CD36 knockouts and CD36 expression cells, showed that co-cultured breast cancer cells have phenotypic changes characteristic of EMT, i.e., dispersed, and elongated." (PMID 34561446, 2021). "We noted significant declines in the level of several transcripts associated with metastasis (Cd36, Egr3, and Maf) and tumorigenesis (Ccr2 and Ccr6) in many solid tumors including breast cancer." (PMID 33682324, 2021). "Early studies suggested that the expression of CD36 was negatively associated with progression and metastasis of breast cancer and was decreased by estradiol in hormone-dependent breast cancer cell lines." (PMID 33232276, 2020). "In line with our findings, lapatinib-resistant cells were reported to upregulate CD36 (FA transporter) expression to enhance exogenous FA uptake, which underlines the role of in situ alterations in lipid metabolism in breast cancer progression." (PMID 32899149, 2020). "In oral squamous cell carcinoma, melanoma and luminal A breast cancer, CD36-positive proportions were highly predisposed to induce metastasis." (PMID 31484922, 2019). "Taken together, our results show that breast-associated adipocytes promote the aggressiveness of breast cancer cells, which is, at least in part, mediated via increased expression of the CD36 fatty acid receptor." (PMID 31847105, 2019).